SGK1 (serum/glucocorticoid regulated kinase 1)
Diseases named in the same sentence as SGK1 in open-access papers (continued):
Sharing a sentence is not in itself a finding about the gene and the disease.
Hypertension (continued). "Likewise, hyperaldosteronism mimics the continuous activation of ENaC and causes hypertension as an outcome of MR-driven SGK1 induction." (PMID 36457711, 2022). "SGK1 participates in facilitating hormonal actions involved in stimulating salt intake and inhibiting renal sodium loss; thereby influencing the long term control of arterial blood pressure, thus contributing to the development of hypertension." (PMID 27517916, 2016). "Indeed, SGK1 activity has been associated with hypertension via upregulation of epithelial sodium channel (ENaC) activity." (PMID 19461886, 2009). "Interestingly, renal effects were observed without an increase in blood pressure or glomerular filtration rate, indicating that an increased SGK1 function could serve as a risk factor for the development of hypertension-independent kidney damage." (PMID 38673987, 2024). "It has been demonstrated to inhibit SGK1 in a variety of pathologies, including hypertension, cancer, osteoporosis, chronic kidney disease, diabetes, and its associated secondary complications." (PMID 40427579, 2025). "SGK1 plays a critical role in the pathophysiology of skeletal diseases, cancer, hypertension, diabetes, and cellular homeostasis." (PMID 40427579, 2025). "Dysregulation of SGK1 expression can lead to various diseases, including hypertension, cancer, and autoimmune, and neurodegenerative diseases." (PMID 40520230, 2025). "In the context of angiotensin II-induced hypertension, the SGK1-FoxO1 signaling pathway has been identified as a pivotal mediator of the imbalance between Th17/Treg cell subsets and inflammatory responses in target organs." (PMID 40427579, 2025). "Sodium chloride (NaCl) activates Th17 and dendritic cells in hypertension by stimulating serum/glucocorticoid kinase 1 (SGK1), a sodium sensor." (PMID 38673987, 2024). "SGK1 is expressed to varying degrees in various types of cells throughout the body, and plays an important role in hypertension, ion channels, oxidative stress, neurological disorders, and cardiovascular regulation." (PMID 39737082, 2024). "Less endothelial dysfunction and blunted hypertension have been found both in SGK1 knockout mice and mice with application of SGK1 inhibitors." (PMID 37559717, 2023). "High levels of expression of SGK1 is also considered a contributing factor to pathological conditions such as hypertension and diabetic nephropathy." (PMID 37079269, 2023). "Serum and glucocorticoid-regulated kinase 1 (SGK1) is expressed in neuronal cells and involved in the pathogenesis of hypertension and metabolic syndrome, regulation of neuronal function, and depression in the brain." (PMID 37371111, 2023). "Intracellular increased Na+ promotes IsoLG-adduct formation, leading to renal inflammation and hypertension; this process is SGK1 mediated." (PMID 37559717, 2023). "High levels of expression of SGK1 is suggested to contribute to pathological conditions such as hypertension and diabetic nephropathy." (PMID 37079269, 2023). "Iso-2 and iso-3 are more stable than iso-1; Therefore, they are considered to be the main players for the role of SGK1 in hypertension." (PMID 36305246, 2022). "Some SNPs in the SGK1 gene have been demonstrated to relate to blood pressure or hypertension, including rs1057293, rs1743966, rs2758151, rs9402571, rs9376026, rs9389154, rs1763509, rs9376026, rs3813344, rs1763498, rs114414980, rs229133, and rs6924468." (PMID 36305246, 2022). "Taken together, these results suggest that cold exposure–induced dysfunction of EDR and hypertension in rats are most likely via aldosterone-mediated, Sgk1-dependent increase in EnNaC expression and activation of EnNaC." (PMID 36278222, 2022). "Future work will include assessing the role of SGK1 inhibition in other AF-related stressors known to activate SGK1 signaling, such as hypertension, and assessment of pharmacologic SGK1 inhibition." (PMID 35998035, 2022).
Hypertension (continued). "The activation of FOXO3a by SGK1 led to fluid retention and hypertension, which would further induce the occurrence of type 2 diabetes." (PMID 35001835, 2022). "This activates SGK-1 and MRs, which leads to sodium retention in kidneys, and eventually hypertension." (PMID 35153813, 2021). "SGK-1, a downstream mediator of Mineral Corticoid receptors (MRs), activates sodium channels (ENaC) which can lead to salt adaptation and eventually hypertension." (PMID 35153813, 2021). "Glucocorticoid Regulated Kinase 1 (SGK1) induced by serum and glucocorticoids triggers a cascade that leads to hypertension by ENaC activation 61-62." (PMID 33110392, 2020). "It is evident that high-fructose intake activates SGK1 in the same way that high-salt intake does during the development of hypertension in SS rats." (PMID 32179549, 2020). "SGK1 protein contributes to the regulation of discrete developmental stages and pathological conditions including hypertension, diabetic neuropathy, ischemia, trauma and neurodegenerative diseases." (PMID 31281445, 2019). "Recent studies show that SGK1 plays a critical role in the regulation of Th17/Treg differentiation in salt-induced inflammation and AngII-induced hypertension." (PMID 30524295, 2018). "It has been reported that SGK1 signaling in T cells promotes hypertension and contributes to end-organ damage." (PMID 30524295, 2018). "Excessive expression and activity of SGK1 participates in the pathophysiology of diverse disorders, such as hypertension, obesity, diabetes, thrombosis, stroke, fibrosing disease, vascular calcification, infertility, autoimmune disease, and tumor growth." (PMID 31225494, 2018). "In Dahl salt-sensitive (DS) rats, which show hypertension with a high salt diet, the renal expression of Sgk1 is elevated greatly." (PMID 27517916, 2016). "These aldosterone-mediated effects together with the aldosterone mediator, SGK-1; are effectively attenuated by the selective MR antagonist spironolactone, supporting the protective effects of MR blockade in hypertension-driven renal injury." (PMID 26730742, 2016). "Glucocorticoids activate the serum glucocorticoid kinase 1 (SGK1) gene, which regulates sodium transporters, leading to hypertension." (PMID 26578982, 2015). "SGK1 is a central molecule in the regulation of renal Na+ handling and in the pathophysiology of hypertension and renal fibrosis." (PMID 24797667, 2014). "Moreover, based on our data, it is conceivable that high dietary phosphate intake might predispose to the development of CKD and hypertension through augmented FGF23-induced SGK1 activation and Na+ retention also in the normal population and that aldosterone might modulate this effect." (PMID 24797667, 2014). "Of these, SGK1 has been studied the most and is believed to be important for renal sodium absorption, salt-sensitivity to hypertension and glycemia, cardiac repolarization, and numerous other processes." (PMID 25033284, 2014). "The implementation of these innovative strategies is expected to facilitate the translation of SGK1-targeted therapies from the laboratory to the clinic, and provide new solutions for the treatment of metabolic bone diseases, diabetes, hypertension, and tumors." (PMID 40427579, 2025). "Such insights may also have significant implications for the development of targeted therapies aimed at modulating SGK1 activity or enhancing ENaC degradation to effectively manage and treat hypertension." (PMID 38732158, 2024). "Interestingly, SGK1 was recently shown to be a key player in hypertension development in response to ANG II or salt." (PMID 38673987, 2024). "Interestingly, SGK1 in T cells and DCs is critical for developing salt-dependent and salt-independent hypertension." (PMID 38673987, 2024). "Therefore, maternal signals mediated by SGK1 participate in the fetal programming of diabetes and hypertension, shedding light on the decisive role of SGK1 in the maternal side of fetal programming." (PMID 38427115, 2024).
Hypertension (continued). "However, we observed significant differences in hypertension, memory T cell formation, and organ dysfunction in mice, indicating a significant role of SGK1 in salt-sensitive hypertension." (PMID 38673987, 2024). "Notably, SGK1 is activated predominantly under pathological conditions, including hypertension, hypertrophic response, heart failure, and other oxidative and mechanical stressors related to electrical remodeling." (PMID 37124559, 2023). "Inhibition of SGK1 in CD11c+ cells by knockdown or pharmacological inhibition can reduce nicotinamide adenine dinucleotide phosphate oxidase and ENaC expression, which plays a protective role against renal inflammation and hypertension." (PMID 37559717, 2023). "It has been demonstrated that excessive SGK1 activity, stimulated by oral NaCl and renal NaCl retention, could lead to development and progression of arterial hypertension." (PMID 35326095, 2022). "SGK1 signaling has also been implicated in murine cardiac inflammation and NLRP3 inflammasome activation resulting from angiotensin II infusion–induced hypertension." (PMID 35998035, 2022). "Hence, dysregulated SGK1 expression can result in multiple diseases, including hypertension, cancer, autoimmunity, and neurodegenerative disorders." (PMID 36457711, 2022). "SGK1 participates in the regulation of hypertension mainly through ENaC." (PMID 36305246, 2022). "Thus, maternal signals mediated by SGK1 play a decisive role in fetal programming of hypertension induced by prenatal protein restriction." (PMID 33195190, 2020). "For example, it has been reported that a modest increase in salt concentration induces SGK1 expression, promotes IL-23R expression, and enhances Th17 cell differentiation in vitro and in vivo, and that SGK1 signaling in T cells promotes hypertension and contributes to end-organ damage." (PMID 30524295, 2018). "In the present study, we evaluated whether SGK1-FoxO1 signaling pathway is involved in Th17/Treg imbalance in AngII-induced hypertension." (PMID 30524295, 2018). "The exact mechanisms by which SGK-1 is involved in hypertension and cardiovascular disease remains to be fully elucidated however they may involve regulation of the transcription factors forkhead transcription factor 3a, beta-catenin and nuclear factor κ B." (PMID 28094006, 2017). "Therefore, SGK1 were expected to participate in the increased salt uptake during pregnancy, contributing to the increase extracellular fluid volume, which favors hypertension of pregnancy." (PMID 27517916, 2016). "However, the cross-talk between SGK1 and the downstream signalling pathways activated in myocardial ischemia and hypertension, respectively, likely lead to disparate outcomes." (PMID 24265802, 2013). "Because small increases in the sodium reabsorptive capacity of the renal epithelia can have dramatic consequences on fluid volume regulation, increased SGK1 expression might contribute to the development of hypertension." (PMID 19461886, 2009). "In addition, SGK1 was found to be a key player in mineralocorticoid/salt-induced hypertension." (PMID 38673987, 2024). "Inhibition of serum/glucocorticoid regulated kinase 1 (SGK1) can reduce the translocation of factor forkhead box O1 (FoxO1) from the cytoplasm to the nucleus, ameliorate the Th17/Treg imbalance, and target organ damage to the heart and kidney in Ang II-induced hypertension mice." (PMID 36911741, 2023). "However, we suspect that the short duration of HFD feeding may not result in increased afterload and that the cardiomyocyte-specificity of SGK1 knockdown would minimize any possible confounding effects of hypertension or vascular resistance in our study." (PMID 35998035, 2022). "Moreover, Sgk1 appears to be critical for the fetal programming of hypertension." (PMID 27517916, 2016).
Hypertension (continued). "We have examined the effect of high glucose on TRPV4 and SGK1 expression in an attempt to better elucidate the role of these regulatory proteins in maintaining cell volume under physical stress and thus preventing the development of secondary hypertension which is often observed in DN." (PMID 23049542, 2012). "Using mice with conditional deletion of SGK1 in T cells, we showed that SGK1 in T cells is necessary for the full development of a hypertensive phenotype in both angiotensin II and DOCA-salt models of hypertension." (PMID 36951464, 2023). "It has been well documented that SGK1 was involved renal function and cardiac fibrosis in DOCA salt- and AngII-induced hypertension." (PMID 30524295, 2018). "We demonstrated that mice lacking SGK1 in T cells exhibited blunted hypertension in response to L-NAME/HS." (PMID 38673987, 2024). "Mice lacking SGK1 in T cells or DCs are protected from hypertension, renal and vascular T cell accumulation and injury in response to salt stress." (PMID 38673987, 2024). "With-no-lysine (WNK) and SGK1 are two important kinases regulating kidney ion channels, and hence involved in kidney sodium reabsorption and hypertension." (PMID 36305246, 2022). "Based on the phenotype of familial hyperkalemia and hypertension (FHHt), and a report that WNK1 could stimulate SGK1 and ENaC, we next generated and characterized WNK1−/− mpkCCD cells, also using the CRISPR/Cas9 system." (PMID 36373794, 2022). "Rats that lack SGK1–/– failed to establish hypertension in response to high salt/high fructose (HS/HF) diet." (PMID 35153813, 2021). "WNK1 activates SGK1, inhibits NEDD4L, enhances ENaC activity and leads to hypertension." (PMID 33110392, 2020). "Finally, we evaluated whether SGK1 inhibition would improve peripheral immune system and prevent renal dysfunction, since previous studies show that peripheral immune system is changed and contributes to blood pressure increase and target organ damage in AngII-induced hypertension." (PMID 30524295, 2018). "SGK-1 knockout mice when treated with excess mineralocorticoid and high salt show no progression of hypertension." (PMID 28094006, 2017). "Although SGK1 knockout mice display no severe defects, excessive expression of SGK1 leads to several disorders including hypertension, obesity, and tumor growth." (PMID 26115433, 2015). "Some of these have effects in animal models of hypertension (e.g. SH2B3/LNK, SGK1, and checkpoint inhibitors) while others have not been extensively studied in hypertension specifically, but are predicted to play an important role on the basis of their known effects on T-cell function." (PMID 36951464, 2023). "‘Unknown I’ contained a diverse set of key driver genes such as SGK1, SIK1 and SLC10A6 (sodium metabolism and hypertension), MT2A and TSC22D3 (glucocorticoid signaling), GADD45G, ERRFI1, GPRC5A, and EGFR (cell growth and apoptosis), and CEBPB, CEBPD, and KCNA5 (heart development and function)." (PMID 25033284, 2014). "Furthermore, it has been shown that SGK1 contributes to cardiac inflammation and fibrosis by mediating nucleotide-binding oligomerization domain-like receptor with pyrin domain 3 (NLRP3) inflammasome activation, and cardiac fibroblast-to-myofibroblast transition in AngII-induced hypertension." (PMID 30524295, 2018). "In our study, we did not observe changes in SGK-1 and NCC in the LLL group, although hypertension was noted." (PMID 35955421, 2022). "Increased SGK1 activity has been suggested to play a pathophysiologic role in kidney damage and CKD progression both in the presence and absence of hypertension." (PMID 34064989, 2021).
Obesity (28 papers, 2013 to 2025). Accumulation of substantial excess body fat. "Obesity is a known risk factor for diabetes, and SGK1 has been identified as a contributing factor to the development of obesity." (PMID 40427579, 2025). "The NLRP3 inflammasome has been implicated in various obesity-related pathologies, including AF, and has been shown to be inhibited by pharmacologic SGK1 inhibition." (PMID 35998035, 2022). "We interrogated this pathway further with flow cytometry and determined that SGK1 genetic inhibition abrogated a trend toward an increased atrial macrophage content caused by obesity." (PMID 35998035, 2022). "SGK1 inhibition is associated with a reduction in spontaneous atrial ectopy as well as AF inducibility in a mouse model of HFD-induced obesity." (PMID 35998035, 2022). "We therefore evaluated the effect of SGK1 inhibition on atrial inflammation caused by obesity with RT-qPCR of inflammatory genes in WT lean, WT obese, and SGK1 DN obese mice." (PMID 35998035, 2022). "The role of SGK1 in the development of obesity is emphasized by the finding that the I6C/E8CC/CT SGK1 variant is related to increased body weight and is more prevalent in patients with type 2 diabetes than in individuals without a family history of diabetes." (PMID 33195190, 2020). "SGK1 participates in the development of obesity, which is well known to cause insulin resistance and eventually leading to type 2 diabetes." (PMID 33195190, 2020). "The region also contains several genes associted with obesity or metabolic syndrome such as ENPP1 with obesity and risk of glucose intolerance and type 2 diabetes, SGK1 with insulin secretion in type 2 diabeties." (PMID 23977060, 2013). "SGK1 exhibits a strong correlation with obesity-associated inflammation, and its overexpression is associated with adipocyte dysfunction, potentially contributing to the development of obesity, diabetes, and metabolic syndrome." (PMID 40004080, 2025). "Constitutive SGK1 activation may modulate AF susceptibility in HFD-induced obesity." (PMID 35998035, 2022). "SGK1 regulates the expression of a number of ion channels, including epithelial sodium channel (ENaC), which is upregulated in obesity and diabetes." (PMID 38935171, 2025). "On the contrary, SGK1 inhibitors (heterocyclic indazole derivatives) are currently being trialed for several pathologies, ranging from diabetes and obesity to kidney disorders." (PMID 40702548, 2025). "Serum- and Glucocorticoid-Regulated Kinase 1 (SGK1) is highly expressed in the human and murine heart and is upregulated in many pathophysiological settings, including obesity, heart disease and diabetes." (PMID 38935171, 2025). "Collectively, these findings indicate that SGK-1 plays a pivotal role in the development of obesity and T2D, which, in turn, contribute to increased morbidity and mortality in OP." (PMID 40427579, 2025). "SGK1 is upregulated in obesity and its genetic inhibition prevents obesity-related atrial fibrillation." (PMID 38483771, 2024). "Specifically, the genetic or pharmaceutical inhibition of SGK1 directly inactivates cardiomyocyte sodium channel currents, or indirectly rescues obesity or AngII-induced AF by reducing myocardial fibrosis and inflammation." (PMID 37580750, 2023). "SGK1 has been shown to regulate glucose levels, affect various physiological functions, and plays an active role in the pathophysiology of obesity, diabetes, autoimmune diseases, and cancer." (PMID 37370761, 2023). "We posit that SGK1 likely interacts with other obesity-related adverse signaling pathways and that inhibiting SGK1 can therefore mitigate the development of AF." (PMID 35998035, 2022). "We then postulated that genetic inhibition of SGK1 would be protective in obesity-related AF through attenuation of obesity-related atrial electroanatomic remodeling and inflammation." (PMID 35998035, 2022).